PRKY (protein kinase Y-linked (pseudogene))
Synonyms: PRKYP; PRKXP3
Gene: Transcribed unitary pseudogene on chromosome Y (7,274,313 to 7,371,868, forward strand). Ensembl gene ENSG00000099725.
Diseases named in the same sentence as PRKY in open-access papers:
PRKY is named in the same sentence as 10 diseases in open-access papers, as found by Europe PMC text mining. Sharing a sentence is not in itself a finding about the gene and the disease. The quoted sentences say what the papers report.
prostate carcinoma (2 papers, 2024 to 2025). A carcinoma that arises from epithelial cells of the prostate gland. "The methylation level of the site cg05163709 on PRKY promoter in urine specimens has already been proven to be associated with Prostate Cancer." (PMID 38468226, 2024). "Radiomic features of magnetic resonance imaging MRI and methylation of the PRKY promoter were found to be associated with prostate cancer." (PMID 38468226, 2024). "Nevertheless, the AUC of the T2WI-methylation-clinic-combined model was still greater than that of any other model in our study, indicating the value of PRKY promoter methylation in the prediction of prostate cancer." (PMID 38468226, 2024).
endometriosis (1 paper, 2019). The growth of functional endometrial tissue in anatomic sites outside the uterine body. "The prevalence and concentration of PCR-positive target inserts for BAGE, PRKY, TTTY9A and ZFY displayed higher values in the fertile, control (FCON) patients compared with the fertile, endometriosis patients (FOE)." (PMID 30760267, 2019).
pancreatic cancers (1 paper, 2025). "Although identifying cancer-subtype biomarker is challenging, UALCAN analysis suggested that the methylation of the PRKY promoter is absent in many other cancers (lung, liver, colorectal, esophageal, bladder, and pancreatic cancers)." (PMID 41008642, 2025).
testicular disorder (1 paper, 2025). A non-neoplastic or neoplastic disorder affecting the testis. "Patients with 46,XX testicular disorder exhibit a translocation between PRKX and reverse protein kinase Y (PRKY) genes." (PMID 39891056, 2025).
cancer (3 papers, 2020 to 2025). A tumor composed of atypical neoplastic, often pleomorphic cells that invade other tissues. "However, to the best of our knowledge, there is no known cellular function of PRKY as well as any reports on its expression in cancer cells." (PMID 32764580, 2020).
PRKY also shares sentences with these, for which no sentence is quoted: amelogenesis imperfecta (1 paper); coronary artery disease (1); schizophrenia (1); tumor (1); vitiligo (1).